WDR76 (WD repeat domain 76)
Description:
Specifically binds 5-hydroxymethylcytosine (5hmC), suggesting that it acts as a specific reader of 5hmC.
Synonyms: FLJ12973; Cmr1; CDW14
Tractability: PROTAC: ubiquitination databases record sites on it.
Gene: Protein-coding gene on chromosome 15 (43,824,498 to 43,868,414, forward strand). Ensembl gene ENSG00000092470.
Subcellular location (Human Protein Atlas): Nuclear bodies; Nucleoli fibrillar center
Gene Ontology:
Molecular function: enzyme binding; protein binding; DNA binding
Biological process: DNA damage response; regulation of DNA damage checkpoint
Cellular component: heterochromatin; nucleus; site of DNA damage
Genetic constraint (gnomAD): Loss-of-function variants: 46 observed, 62.44 expected, observed/expected ratio (o/e) 0.74, 90% interval 0.58 to 0.94. The upper end of that interval is the gene's LOEUF score, 0.94, which puts it in group 3 of 6, group 1 being the genes least tolerant of losing a copy. Missense variants: 574 observed, 634.1 expected, observed/expected ratio (o/e) 0.91, 90% interval 0.85 to 0.97. Synonymous variants: 228 observed, 224.11 expected, observed/expected ratio (o/e) 1.02, 90% interval 0.91 to 1.13.
Homologues: Orthologues: macaque WDR76 (96% identical), chimpanzee WDR76 (96% identical), pig WDR76 (84% identical), dog WDR76 (82% identical), rabbit WDR76 (82% identical), guinea pig WDR76 (74% identical), mouse Wdr76 (71% identical), rat Wdr76 (69% identical), tropical clawed frog wdr76 (35% identical), zebrafish wdr76 (31% identical).
Diseases named in the same sentence as WDR76 in open-access papers:
WDR76 is named in the same sentence as 20 diseases in open-access papers, as found by Europe PMC text mining. Sharing a sentence is not in itself a finding about the gene and the disease. The quoted sentences say what the papers report.
liver cancer (6 papers, 2019 to 2026). An epithelial or non-epithelial malignant neoplasm that arises from the liver. "Up to now, the research of WDR76 on cancer regulation is mainly focused on the occurrence and development of liver cancer and colorectal carcinoma." (PMID 37081180, 2023). "Until now, WDR76 has shown to play a vital role in types of cancer, such as liver cancer and colorectal cancer (CRC)." (PMID 33714259, 2021). "Our in vitro studies reveal that RAS degradation mediated by WDR76 is directly related to the inhibition of proliferation, transformation, and invasion of liver cancer cells." (PMID 30655611, 2019). "Current literatures have shown that WDR76 function as tumor suppressor in colorectal, bladder, colon and liver cancer, showing that it may also be potential marker for treatment response in melanoma." (PMID 40420636, 2026). "Recently, a research group found that WD repeat domain 76 (WDR76) promotes the polyubiquitination-dependent degradation of RAS, which results in the inhibition of proliferation, transformation, and invasion of liver cancer cells." (PMID 38124228, 2023). "WDR76-mediated RAS destabilization results in the inhibition of proliferation, transformation, and invasion of liver cancer cells." (PMID 30655611, 2019). "Overall, our results indicated that cytoplasmic WDR76 plays role in RAS destabilization and in suppression of liver cancer cells transformation." (PMID 30655611, 2019). "As a cancer suppressor in hepatocellular carcinoma (HCC), WDR76 acts as an E3 ubiquitin ligase and mediates the polyubiquitination of RAS, leading to the inhibition of proliferation, transformation, and invasion of liver cancer cells." (PMID 38173030, 2024). "For example, WDR76 has been demonstrated to play a role as an E3 linker protein to mediate the polyubiquitination-dependent degradation of RAS, leading to the inhibition of proliferation, transformation, and invasion of liver cancer cells." (PMID 37081180, 2023). "In vivo and in vitro studies demonstrated that cytoplasmic WDR76 directly mediated RAS polyubiquitination degradation through binding to HRAS, resulting in inhibition of proliferation, transformation, and the invasive ability of liver cancer cells." (PMID 33714259, 2021).
hepatocellular carcinoma (5 papers, 2019 to 2024). A malignant tumor that arises from hepatocytes. "WDR76 (WD Repeat protein 76) is an E3 ligase that suppresses tumorigenesis of human hepatocellular carcinoma (HCC) cells by destabilizing RAS." (PMID 31362761, 2019). "WDR76 was also recently reported as a tumour suppressor in hepatocellular carcinoma." (PMID 31870430, 2019). "WD Repeat protein 76 (WDR76) mediates the polyubiquitination-dependent degradation of RAS in hepatocellular carcinoma (HCC)." (PMID 31362761, 2019). "Here, we identify WD40-repeat protein 76 (WDR76) as one of the HRAS binding proteins using proteomic analyses of hepatocellular carcinomas (HCC) tissue." (PMID 30655611, 2019). "To validate the possible tumor-suppressive role of WDR76 in human HCC, we analyzed a tissue microarray (TMA; LV1505; US Biomax) consisting of 46 cases of human hepatocellular carcinoma with paired adjacent non-tumor tissues." (PMID 30655611, 2019). "Using a proteomics approach with tumor and non-tumor tissues from a human patient with hepatocellular carcinoma (HCC), the E3 linker protein, WDR76, was identified as an HRas binding protein, which promoted HRas degradation, thus functioning as a tumor suppressor in liver cancer." (PMID 31873167, 2019).
lung carcinoma (4 papers, 2021 to 2025). "A recent research indicated that WDR76 could activate lipid metabolism-associated genes to inhibit ferroptosis in dependent manner of lymphoid-specific helicase (LSH) which acted as an oncogene in lung cancer." (PMID 34707943, 2021). "Lymphospecific helicase (LSH) in lung cancer activates metabolic genes by modifying DNA methylation through WD repeat domain 76 (WDR76) to reduce lipid ROS levels and inhibit ferroptosis, where LSH action is antagonized by DDB1- and CUL4-associated factor 8 (DCAF8)." (PMID 40327848, 2025). "Furthermore, the Human Protein Atlas lists WDR76 as an unfavorable prognostic marker in various cancers including lung cancer." (PMID 34707943, 2021).
colorectal cancer (3 papers, 2019 to 2023). A primary or metastatic malignant neoplasm that affects the colon or rectum. "A lower level of WDR76 was associated with poor survival of colorectal cancer patients." (PMID 33282547, 2020). "In colorectal carcinoma, WDR76 could degrade pan-RAS and inhibit cancer stem cell activation, as well as the progression of colorectal carcinoma cell cycle by degrading KRAS, thereby damaging the tumor development." (PMID 37081180, 2023).
lung adenocarcinoma (3 papers, 2021 to 2024). A carcinoma that arises from the lung and is characterized by the presence of malignant glandular epithelial cells. "By bioinformatics research, WDR76 also participates in the manipulation of immune invasion of lung adenocarcinoma, exerting a predictive value for the prognosis of lung adenocarcinoma." (PMID 37081180, 2023). "This study aimed to evaluate the role of WDR76 in the prognosis and immune infiltrates of lung adenocarcinoma (LUAD)." (PMID 34707943, 2021).
colon cancer (2 papers, 2019 to 2023). "Bioinformatic analysis revealed the higher expression of WDR76 in 5-FU sensitive colon cancer cells compared to resistant colon cancer cells, accompanied by the decreased mRNA expression of WDR76 in 5-FU resistant colon cancer cells." (PMID 37081180, 2023). "Our findings demonstrated a role of WDR76 as a promising target for reversing the resistance of colon cancer to 5-FU." (PMID 37081180, 2023). "The overexpressed WDR76 resulted in the apoptosis and the downregulated colony numbers in 5-FU resistant colon cancer cells, leading to the elevated sensitivity of 5-FU." (PMID 37081180, 2023). "Meanwhile, knockdown of WDR76 enhances the resistance of 5-FU in colon cancer both in vitro and vivo, which was reversed by a specific inhibitor of HRAS, Kobe006." (PMID 37081180, 2023). "Our study indicated that WDR76/HRAS axis could reversely manipulate the sensitive of resistant colon cancer cells to 5-FU." (PMID 37081180, 2023). "These outcomes indicated that WDR76 could regulate the sensitivity of resistant colon cancer cells to 5-FU." (PMID 37081180, 2023). "In the present study, the potential relationship between WDR76 and 5-FU sensitivity of colon cancer was explored and experimentally verified by bioinformatics analysis depending on GEO database, to provide novel biomarkers and/or targets for treatment of colon cancer." (PMID 37081180, 2023). "The WDR76/HRAS axis might serve as an effective target of 5-FU resistance in colon cancer." (PMID 37081180, 2023).
Hepatic steatosis (2 papers, 2019 to 2021). Steatosis is a term used to denote lipid accumulation within hepatocytes. "In summary, our data indicated that WDR76 plays a role as a positive regulator of diet-induced obesity and hepatic steatosis in mice through HRas destabilization." (PMID 31873167, 2019). "To further investigate the role of WDR76 in hepatic steatosis, we analyzed the expression of key lipogenic and metabolic genes in the livers of HFD-fed Wdr76+/+ and Wdr76−/− mice." (PMID 31873167, 2019). "Consistently, hepatic gene expression profiles of lipogenesis and gluconeogenesis in the HFD-fed Wdr76Li-TG mice were increased, suggesting that WDR76 promotes HFD-induced hepatic steatosis." (PMID 31873167, 2019). "Because Wdr76−/− mice exhibited decreased hepatic steatosis, we examined the impact of WDR76 in the liver by using liver-specific Wdr76 transgenic mice (Wdr76Li−TG)." (PMID 31873167, 2019). "We therefore investigated the roles of the Ras destabilizer WDR76 in preadipocyte differentiation using 3T3-L1 cells, and in obesity and hepatic steatosis using a HFD-induced obesity model." (PMID 31873167, 2019). "Taken together, the results showed that Wdr76−/− mice had reduced hepatic steatosis." (PMID 31873167, 2019). "Because hepatic PPARγ and C/EBPα proteins are known to play a role in the development and maintenance of hepatic steatosis, we assessed the expression levels of these in the liver tissues of HFD-fed Wdr76+/+ and Wdr76−/− mice." (PMID 31873167, 2019). "Our findings suggest that WDR76 controls HFD-induced obesity and hepatic steatosis via HRas destabilization." (PMID 31873167, 2019). "Moreover, we further characterized the roles of WDR76 in HFD-induced obesity and hepatic steatosis, suggesting WDR76 as a potential target for the treatment of obesity and metabolic diseases related to HFD." (PMID 31873167, 2019). "As hepatic steatosis is one of the factors that can progress to HCC; hence this study provided new insights into the potential targeted treatment of hepatic steatosis through regulation of WDR76 expression to prevent the transformation of liver cells into cancer cells." (PMID 33714259, 2021). "However, HFD-fed Wdr76−/− mice showed decreased lipid storage in adipose tissue as results of size reduction of WATs but do not exhibit increased circulating TG levels or hepatic steatosis compared with Wdr76+/+ mice." (PMID 31873167, 2019). "However, the physiological roles of HRas protein stability regulation by WDR76 in HFD-induced obesity and hepatic steatosis are unknown." (PMID 31873167, 2019).
anaplastic astrocytoma (1 paper, 2024). "Moreover, the highest expression of WDR76 was found in the histological type of anaplastic astrocytoma (AA) in TCGA database and in recurrent anaplastic oligodendroglioma (rAO) in the CGGA database." (PMID 38173030, 2024).
glioma (1 paper, 2024). A benign or malignant brain and spinal cord tumor that arises from glial cells (astrocytes, oligodendrocytes, ependymal cells). "Taken together, this study is the first to confirm WDR76 as a prognostic risk factor for lower grade glioma, which may influence the progression of malignancy through its involvement in the cell cycle and the Notch signaling pathway." (PMID 38173030, 2024). "This study not only expands knowledge on the molecular function of WDR76, but also provides a promising target molecule for future precision therapies and immunotherapy of lower grade glioma, offering insights to improve patient survival outcomes." (PMID 38173030, 2024). "Furthermore, WDR76 mediates tumor immunity in lower grade glioma by regulating the infiltration of immune cells such as M2 macrophages into the immune microenvironment." (PMID 38173030, 2024).
Hepatic fibrosis (1 paper, 2019). The presence of excessive fibrous connective tissue in the liver. "We also found severe hepatic fibrosis with Ras increment in livers from 1-year-old WDR76−/− mice, but not in livers from same age WDR76+/+ mice." (PMID 30655611, 2019).
hyperlipidemia (1 paper, 2019). "The HFD-fed Wdr76−/− mice showed improved metabolic and physiological parameters, including decreased obesity, insulin resistance, and hyperlipidemia with increases of HRas levels compared with Wdr76+/+ mice." (PMID 31873167, 2019). "Wdr76−/− mice are resistant to HFD-induced obesity, insulin resistance and hyperlipidemia with an increment of HRas levels." (PMID 31873167, 2019).
Insulin resistance (1 paper, 2019). Increased resistance towards insulin, that is, diminished effectiveness of insulin in reducing blood glucose levels. "Wdr76−/− mice had improved glucose tolerance and insulin sensitivity, suggesting that WDR76 deficiency could reduce HFD-induced insulin resistance." (PMID 31873167, 2019). "In contrast, liver-specific Wdr76 transgenic mice (Wdr76Li-TG) were characterized showing increased HFD-induced metabolic defects including obesity and insulin resistance with reduced HRas levels." (PMID 31873167, 2019).
Obesity (1 paper, 2019). Accumulation of substantial excess body fat. "The role of WDR76 in adipocyte hypertrophy was confirmed by in vivo experiments using a HFD-induced obesity model." (PMID 31873167, 2019). "The roles of WDR76 in obesity and metabolic regulation were characterized using a high-fat diet (HFD)-induced obesity model using Wdr76−/− mice and liver-specific Wdr76 transgenic mice (Wdr76Li−TG)." (PMID 31873167, 2019). "Although WDR76 was specifically overexpressed in the liver, Wdr76Li−TG mice showed a severe obesity phenotype after HFD feeding when compared with Wdr76+/+ mice." (PMID 31873167, 2019). "Moreover, further studies using adipose or liver tissue-specific Wdr76 knockout mice and validating the role of WDR76 in adipogenesis in vivo will help to clarify the roles of WDR76 in metabolism and as a potential therapeutic target to control obesity-associated metabolic diseases." (PMID 31873167, 2019). "Based on the knockout mouse experiments, we hypothesized that Wdr76Li−TG mice will be more sensitive to the HFD, resulting in a severe obesity phenotype compared with Wdr76+/+." (PMID 31873167, 2019).
tumor (16 papers, 2019 to 2026). "The role of WDR76 as a tumor suppressor is also revealed by the high susceptibility to diethylnitrosamine (DEN)-induced inflammation, fibrosis, HCC progression, and lung metastasis in WDR76−/− mice compared with those in wild-type (WT) mice." (PMID 30655611, 2019). "Together, our results indicated that in APC-mutated CRC tumors, WDR76 plays a role as a tumor suppressor by repressing RAS protein abundance and thus reducing the activation of the Wnt/β-catenin pathway." (PMID 31362761, 2019). "IHC staining showed that the expression level of Ki‐67 and WDR76 was decreased in xenograft tumours induced by LRPPRC knockdown in MDA‐MB‐231 cells, while the inhibitor of glutaminase BPTES further lowered the level of Ki‐67." (PMID 38372449, 2024). "This study further expands the molecular function of WDR76 in LGG pathogenesis and tumor immunity, revealing the underlying mechanisms of the malignant progression of LGG and opening up a wider field for future research." (PMID 38173030, 2024). "Meanwhile, we found that the expression of WDR76, as a tumour suppressor, was significantly reduced upon LRPPRC knockdown among 68 candidate genes screened." (PMID 38372449, 2024). "The results reveal an association of the hsa_circ_0000417/hsa_circ_0002688/hsa_circ_0001387-hsa-miR-199a-5p-WDR76 regulatory axis with survival prognosis, tumor-infiltrating immune cells, immune escape, pathway activity, and drug sensitivity in HCC patients." (PMID 36878930, 2023). "Based on the studies available, WDR76 is identified as a novel tumor suppressor and RAS activity can be controlled via regulating protein stability which further affect the tumorigenesis and metastasis in different cancer diseases." (PMID 33714259, 2021). "The gene expression level of WDR76 was significantly higher in tumor samples than that in normal tissue samples in TCGA database (P < 0.001)." (PMID 34707943, 2021). "WDR76 functioned as a tumor suppressor mainly via degradation of RAS and then deactivation of Wnt/β-catenin signaling." (PMID 33282547, 2020). "Immunohistochemical (IHC) analyses of these tissues revealed that RAS levels were higher in 41/46 (89.1%) HCC patient tumors compared with their adjacent non-tumor tissues, whereas WDR76 expression levels were lower in 34/46 (73.9%) of HCC tumors." (PMID 30655611, 2019). "Degradation of Ras in the HRasG12V-induced HCC model by crossing HRasG12V mice with WDR76 Tg mice resulted in a significant reduction in tumor incidence." (PMID 30655611, 2019). "We recently verified the tumor-suppressive role of WDR76, which functions via Ras degradation, by monitoring effects the diethylnitrosamine (DEN)-induced heptocarcinogenesis in Wdr76−/− mice and the HRasG12V-driven liver carcinogenesis in Wdr76Li-TG mice." (PMID 31873167, 2019). "WDR76 deficiency resulted in enhanced development of DEN-induced HCC phenotypes, including promoted tumor formation, and increment in liver weight and liver/body weight ratios." (PMID 30655611, 2019). "We recently identified WDR76, a component of E3 ubiquitin ligase complex, as one of the HRas binding proteins that mediates Ras degradation, thus functioning as a tumor suppressor in liver cancer and colorectal cancer." (PMID 31873167, 2019). "WDR76-mediated Ras degradation and its tumor-suppressive role were consistently verified by comparing liver tissues of WDR76+/+ versus WDR76−/− mice and HRasG12V versus HRasG12V/WDR76 Tg mice." (PMID 30655611, 2019). "The Wdr76−/−; ApcMin/+ mice exhibited increases in both the number and the size of tumors in the small intestine compared with 15-week-old age-matched Wdr76+/+; ApcMin/+ mice, indicating that Wdr76 plays a role as a tumor suppressor in the small intestine." (PMID 31362761, 2019). "At 52-weeks of age, significant decreases in liver weights and liver/body weight ratios which is an indicator of tumor burden were evident in HRasG12V/WDR76 Tg mice compared with HRasG12V mice." (PMID 30655611, 2019).